CXCL2 (C-X-C motif chemokine ligand 2)
Diseases named in the same sentence as CXCL2 in open-access papers (continued):
Sharing a sentence is not in itself a finding about the gene and the disease.
pancreatic cancer (17 papers, 2016 to 2025). "Recently, a study found that melatonin promoted the infiltration of N1 subtype neutrophils by CXCL2, which killed pancreatic cancer cells by NET-derived ROS, indicating the antitumor effect of NETs." (PMID 38023616, 2023). "Among a variety of chemokines/cytokines known to recruit and/or generate MDSCs in tumor sites, we found significant elevations in Cxcl1, Cxcl2, Csf2, and Tgfb1 in the pancreatic tumor tissues of PKR mice." (PMID 37814340, 2023). "Although ELMO2 has not been subject to extensive research in cancer, a recent study has reported that ELMO2 plays an important role in chemotaxis, invasion and migration mediated by CXCL-2 in pancreatic cancer." (PMID 36551595, 2022). "The knockdown of oncogenes MYEOV and DDX60L inhibited the expression of CXCL2 in pancreatic cancer cells." (PMID 34789165, 2021). "With the Kaplan–Meier Plotter analysis, the expression of CXCL2 in pancreatic cancer significantly affects the prognosis of patients (n = 177), and high expression levels are associated with a poor prognosis." (PMID 34789165, 2021). "Data from TCGA (the Cancer Genome Atlas database) revealed that the expression levels of CXCL2/3/5/6/7/8/9/10/13/14/16/17 were significantly higher in pancreatic cancer tissues than normal tissues (all p-value < 0.05)." (PMID 34497764, 2021). "Additionally, the higher expression of the human homolog of mouse Cxcl5, CXCL6, and other ligands of CXCR2 (CXCL1 and CXCL2) was also identified in human pancreatic cancer cells after adding AMP." (PMID 37867243, 2023). "We found higher levels of Cxcl1, Cxcl2, and TGFβ mRNAs bound to mutant Regnase-1 protein than those bound to wild-type Regnase-1 protein, suggesting that Regnase-1 may directly bind to and degrade these cytokines/chemokines in pancreatic tumor cells." (PMID 37814340, 2023). "Downregulating MYEOV can inhibit the expression of CXCL2 in pancreatic cancer cells, and the CXC chemokine CXCL2 has strong neutrophil chemotactic activity." (PMID 40535130, 2025). "Accordingly, we showed in pancreatic cancer cells (KPC) in vitro an induction of monocyte/macrophage-chemoattractant cytokines such as CCL2/MCP1, CCL20/MIP3α, CXCL2/MIP2α and also GM-CSF by Juzentaihoto (and the combination)." (PMID 39723364, 2024). "Mechanistically, Regnase-1 directly negatively regulated a variety of chemokines/cytokines important for MDSC recruitment and activation, including CXCL1, CXCL2, CSF2, and TGFβ, in pancreatic cancer cells." (PMID 37814340, 2023). "Other members of the C-X-C motif chemokine family were found to be upregulated in pancreatic cancer cells after Rintatolimod treatment, like CXCL 1, CXCL2, CXCL3, CXCL8 (IL-8), CXCL11, CXCL14, and CXCL16." (PMID 34207861, 2021). "Serum levels of GM-CSF in pancreatic cancer patients are also significantly higher than in healthy individuals, and increased expression of the inflammatory cytokines IFN-γ, CXCL1 and CXCL2 were observed in a mouse model of spontaneous pancreatic cancer." (PMID 29245934, 2017). "Furthermore, senescence-induced pancreatic stellate cells secrete CXCL1, CXCL2, and CXCL3, and blockade of the CXCR2 axis suppresses pancreatic cancer cell proliferation." (PMID 41155662, 2025). "Furthermore, we identified CXCL1, CXCL2, and CXCL3 as SASP factors secreted by senescence-induced hPSCs, and the inhibition of the CXCLs/CXCR2 axis attenuated their stimulating effects on the proliferation and migration of pancreatic cancer cells." (PMID 36012531, 2022).
Stroke (16 papers, 2013 to 2025). Sudden impairment of blood flow to a part of the brain due to occlusion or rupture of an artery to the brain. "Clinical meta‐analyses and cohort datasets have demonstrated that elevated levels of Il6, Il1β, Cxcl2, and Cxcl10 are closely associated with poorer stroke prognosis." (PMID 40585759, 2025). "In summary, our results demonstrate that stroke‐induced brain border expansion and infiltration of CXCL2+ neutrophils which showed a great tendency to form NETs and dampened subsequent vascular reperfusion." (PMID 39135337, 2024). "Here, we compared single‐cell RNA sequencing data of skull, meningeal, and femur and found that stroke triggered the generation of CXCL2+ neutrophils from meningeal." (PMID 39135337, 2024). "Together, these findings suggest CXCL2‐induced NETs formation by neutrophils, and that CXCL2 neutralization can enhance vascular reperfusion and improve stroke outcome." (PMID 39135337, 2024). "We reported a key role of CXCL2+ neutrophils in the formation of neutrophil extracellular traps (NETs) in the acute phase after reperfusion injury of stroke, resulting in worsened neurological outcomes." (PMID 39135337, 2024). "In our study, we found that CXCL2 neutralization inhibited the formation of NETs by neutrophils, thereby improving vascular reperfusion 3 days after stroke." (PMID 39135337, 2024). "The increased CXCL-1 and CXCL-2 levels in the brain tissue after stroke lead to accelerated leukocytes and particularly granulocyte accumulation and aggravate ischaemic tissue damage." (PMID 30700305, 2019). "In ET-1 induced experimental stroke a significant increase in CXCL2 expression at 24 h after brain ischemia induction was also observed." (PMID 24324296, 2013). "We next investigated whether CXCL2 neutralization could inhibit neutrophil infiltration and improve stroke outcome." (PMID 39135337, 2024). "As accumulation of NET exacerbates neuroinflammation and worsen the prognosis of stroke patients, we sought to investigate whether CXCL2 drives NETs formation by neutrophils." (PMID 39135337, 2024). "Furthermore, CXCL2‐neutralizing antibody treatment reduced brain infarcts and improved vascular reperfusion at day 3 postischemic stroke." (PMID 39135337, 2024). "Next, we examined the mRNA expression of CXCL1 and CXCL2 in the lung after stroke." (PMID 31447768, 2019). "The data showed that the expression of CXCL2 was significantly increased after stroke." (PMID 31447768, 2019). "After stroke, CBM neutrophils preferentially increased the expression levels of Cxcl2, Prok2, Ngp, Thbs1, and Cd177." (PMID 39930981, 2025). "We found that stroke induced an expansion of the CXCL2+ neutrophil phenotype in the meninges, and neutrophil maturation increased, suggesting that ischemic stroke‐induced CXCL2+ neutrophils at the brain border may also be an aging‐associated secretory phenotype." (PMID 39135337, 2024). "When comparing SHR and WKY subjected to stroke, we observed a significantly higher expression of CCL2, CCL7, and CXCL2 in SHR." (PMID 26640428, 2015). "Accordingly, we show that sequestering CXCL2 using a neutralizing antibody injected into the cisterna magna attenuates neutrophil-specific recruitment into the brain after stroke in WT but not Mrgprb2−/− mice." (PMID 40712576, 2025). "In line with Trizol whole-brain mRNA data, Cxcl1 and Cxcl2 levels were profoundly ﻿reduced in Il1−/− mice 24 h after stroke, whereas Ccl2 was not significantly downregulated in input material from Il1−/− mice." (PMID 35384588, 2022). "Interestingly, Cxcl1 expression was persistently reduced 72 h after stroke in Il1−/− mice, whereas Cxcl2 and Ccl2 already tended to normalize to WT levels." (PMID 35384588, 2022). "However, the expression of CCL2, CCL3, CCL4, CCL7, and CXCL2 was strongly increased after stroke, whereas CCL19, CCL20, and CXCL5 expression levels were not changed." (PMID 26640428, 2015).
Stroke (continued). "Although the expression of several studied chemotactic inflammatory mediators (chemokines CCL2, CCL3, CCL5, and CXCL2) was significantly increased in the early stage of this stroke model, there was no clear correlation between this expression and intensity of neurodegeneration (data not shown)." (PMID 24324296, 2013).
pulmonary fibrosis (15 papers, 2017 to 2025). Chronic progressive interstitial lung disorder characterized by the replacement of the lung tissue by connective tissue, leading to progressive dyspnea, respiratory failure, or right heart failure. "Diseases that were significantly associated with CXCL2 include cholestasis, inflammation, acute lung injury, pulmonary fibrosis and hypertension, and those that were significantly associated with MLF1 was stomach neoplasms." (PMID 41378129, 2025). "CCL5 is known to be a profibrotic SASP while increased expression of CXCL2 is strongly associated with radiotherapy-induced lung fibrosis." (PMID 37460469, 2023). "CXCL2 is significantly upregulated in mouse lung tissue in a bleomycin-induced model of pulmonary fibrosis, and 5-azacytidine (a DNA methyltransferase inhibitor) reduces CXCL2 expression." (PMID 37122736, 2023). "Taken together, these data support a critical role for NFATc3 in regulating the production of CCL2 and CXCL2 in macrophages during the BLM-induced pulmonary fibrosis progression in mouse models." (PMID 37523510, 2023). "An early study reported that CXCL2 regulates angiogenesis and neutralizing anti-CXCL2 antibody significantly reduced BLM-induced pulmonary fibrosis." (PMID 37523510, 2023). "Few studies have addressed the mechanism of CXCL2 in the lung during the development of pulmonary fibrosis." (PMID 37523510, 2023). "To further confirm the role of CXCL2 in NFATc3-mediated pulmonary fibrosis, we administered recombinant mouse CXCL2 (rmCXCL2), intratracheally into NFATc3+/- mice, 8 days after BLM (i.t) stimulation." (PMID 37523510, 2023). "Then, we assessed whether NFATc3 regulates the production of CCL2 and CXCL2 in mouse in vivo pulmonary fibrosis models." (PMID 37523510, 2023). "In addition, C-X-C Motif Chemokine Ligand 2 (CXCL2) was associated with hypertensive disease, inflammation, myocardial ischemia, and pulmonary fibrosis." (PMID 34440025, 2021). "Indeed, Cxcr2 antagonism attenuated lung angiogenesis and fibrosis in mice challenged with bleomycin, supporting that Cxcl2 is an important angiogenic factor that may regulate pulmonary fibrosis development in mice." (PMID 39768150, 2024). "Deficiency in NFATc3 significantly reduces the levels of fibrotic markers CCL2 and CXCL2 induced by BLM, attenuating BLM-induced pulmonary fibrosis and inflammatory response." (PMID 39301028, 2024). "NFATc3+/+ mice subjected to BLM-induced pulmonary fibrosis showed increased accumulation of fibroblast foci, extracellular matrix protein deposition, fibrotic markers and CCL2 and CXCL2 production." (PMID 37523510, 2023). "It was observed that when CCL6 was neutralized in BLM-induced lung fibrosis, the expression levels of CCL3, CXCL1, CXCL2 and IL-1β were significantly reduced, indicating the effects of CCL6 on these chemokines and cytokine (sFigure 6B)." (PMID 36934284, 2023). "Collectively, our data demonstrate, for the first time, that NFATc3 regulates pulmonary fibrosis by regulating CCL2 and CXCL2 gene expression in macrophages." (PMID 37523510, 2023). "Mechanistic studies revealed that NFATc3 is involved in the pathogenesis of pulmonary fibrosis by promoting CCL2 and CXCL2 production in response to damaged epithelial cells, IL-33 and Th2 cytokine stimulation." (PMID 37523510, 2023). "Our analysis showed that eight genes (CSF2, CSF3, CXCL2, CXCL8, IL1B, IL6, MMP9, and TNF) are significantly overlapping with the lung fibrosis pathway with p-value 9.35e-11." (PMID 33362771, 2020). "MIP2 is known as C-X-C motif chemokine 2 (CXCL2) and has been shown to stimulate the migration and activation of neutrophils; neutralization of MIP2 attenuates bleomycin-induced pulmonary fibrosis." (PMID 28304344, 2017). "Cxcl2 depletion in vivo significantly reduced bleomycin-induced pulmonary fibrosis without changes in pulmonary neutrophil influx, fibroblast proliferation, or collagen gene expression." (PMID 39768150, 2024).
pulmonary fibrosis (continued). "Interestingly, NFATc3+/+ mice subjected to BLM-induced pulmonary fibrosis showed increased accumulation of fibrotic foci, extracellular matrix protein deposition, fibronectin, α-SMA, CCL2 and CXCL2 production." (PMID 37523510, 2023). "Moreover, IL-33 treatment increases CCL2 and CXCL2 production in NFATc3+/+ macrophages, but not in NFATc3+/- mice, suggesting that NFATc3 regulates pulmonary fibrosis by regulating CCL2 and CXCL2 expression in macrophages." (PMID 39850880, 2024).
rheumatoid arthritis (15 papers, 2016 to 2024). A chronic, systemic autoimmune disorder characterized by inflammation in the synovial membranes and articular surfaces. "Besides its role as chemoattracting molecule for neutrophils, CXCL2 has been associated with increased osteoclastogenesis in rheumatoid arthritis-associated bone erosion." (PMID 29850558, 2018). "Meanwhile, IL-17 signaling, rheumatoid arthritis, and TNF signaling KEGG pathways were all linked to the cytokine–cytokine receptor interaction pathway through expression of CXCL2." (PMID 35881197, 2023). "It is also reported that CXCL2 is significantly elevated in the serum of rheumatoid arthritis compared to healthy controls." (PMID 36911677, 2023). "The Enrichr pathway assignment analysis (KEGG 2021 Human database) additionally revealed enrichment of chemokine encoding genes (CXCL1, CXCL2, CXCL3, CXCL6, CXCL5, CXCL8, CCL2) which were aligned to several pathways like amoebiasis and rheumatoid arthritis." (PMID 35646693, 2022). "In our analysis, the hub-DEGs TLR2 and CXCL2 significantly enriched the rheumatoid arthritis pathway which indicates that these genes may have the antagonized property against the COVID-19 infection." (PMID 35277538, 2022). "For example, CXCL2 is related to bone erosion in rheumatoid arthritis." (PMID 35468838, 2022). "The DEGs which contributed to the pathway term “Rheumatoid arthritis” were CXCL8 (C-X-C Motif Chemokine Ligand 8), CTSL (Cathepsin L), CXCL2 (C-X-C Motif Chemokine Ligand 2), and CCL2 (C-C Motif Chemokine Ligand 2)." (PMID 36911677, 2023). "Each of three pathway categories legionellosis, amoebiasis and rheumatoid arthritis was enriched by two hub-DEGs (TLR2 and CXCL2)." (PMID 35277538, 2022). "For example, CXCL8, CXCL2, or GRO1 were involved in rheumatoid arthritis, legionellosis, salmonella infection, and so on." (PMID 31921295, 2019).
glioblastoma (14 papers, 2015 to 2025). The most malignant astrocytic tumor (WHO grade IV). "CXCL2 has been reported to facilitate myeloid cell migration and CD8+ T-cell exhaustion, causing accelerated tumor growth and invasion in glioblastoma." (PMID 35912252, 2022). "The chemokine genes MIF, CCL2, CXCL8, CX3CL1 and CXCL2 were all highly expressed by the six glioblastoma primary lines." (PMID 36430641, 2022). "Looking further, the overexpression of CXCL1 and CXCL2 was closely related to glioblastoma’s aggressiveness, facilitating the migration of myeloid cells and, simultaneously, disrupting the accumulation of CD8+ T-cells at the tumor site, thus instigating cancer progression." (PMID 36980182, 2023). "However, further studies are warranted to fully understand the impact of the CXCL2/IL8/CXCR2 axis on glioblastoma as well as the possible role of interference with this signaling in future therapy approaches." (PMID 33807899, 2021). "Thus, the CXCL2/IL8/CXCR2 axis could be a relevant pathway to circumvent the disturbance of the VEGF/VEGFR signaling in glioblastomas to maintain tumor angiogenesis." (PMID 33807899, 2021). "Elevated levels of CXCL1 or CXCL2 promote myeloid cell migration while disrupting the accumulation of CD8 T cells at the tumor site, leading to accelerated glioblastoma progression." (PMID 39660865, 2025). "Recently, besides VEGF, an alternative angiogenic signaling pathway via CXCL2/CXCL8 and its receptor CXCR2 was identified as an essential part of angiogenesis in glioblastoma." (PMID 35269652, 2022). "We aimed to evaluate the angiogenic capacity of CXCL2 and IL8 affecting human endothelial cells to clarify their potential role in glioblastoma (GBM) angiogenesis." (PMID 33807899, 2021). "In our study, we defined expression and significance of VEGF-alternative proangiogenic factors like CXCL2 and IL8 in human glioblastoma tissues." (PMID 33807899, 2021). "The release of CXCL2 activated CXCR2 and the blockade of CXCR2 signaling hindered macrophage-like cell migration that was triggered by programmed cell death 10 (PDCD10)-overexpressed glioblastoma cells." (PMID 39007996, 2024). "Moreover, Kammerer and co-workers observed significant upregulation of inflammation-related genes, including CXCL2, CXCL3, IL1A, and IL6 receptor (IL6R)) after non-lethal 5-ALA-PDT in a panel of prostate and glioblastoma cell lines." (PMID 26705830, 2015).
Obesity (14 papers, 2016 to 2025). Accumulation of substantial excess body fat. "CXCL2 and Cox-2 represent pro-inflammatory wound proteins and are associated with a prolonged wound inflammation in obesity-impaired wound healing conditions." (PMID 27992530, 2016). "Since hypertrophied white adipose tissue produces chemokines, CXCL2 expression is increased in osteoclastogenesis compared with osteoblastogenesis, and white adipose tissue is activated by CXCL2 to prevent the onset of obesity." (PMID 35328013, 2022). "In obesity, adipocytes produced several chemokines (Cxcl2, Cxcl12, Ccl2, etc.)recruiting macrophage and neutrophils, causing systemic inflammation, insulin resistance, and the dysfunction of local endothelial cells." (PMID 34722509, 2021). "Serum levels of numerous obesity-linked chemokines promoting adipocyte proliferation (TIMP-1) and adipose macrophage infiltration (CXCL1, CXCL2, CXCL12, CCL3, and CCL5) were found to be significant predictors of in vivo hippocampal TSPO signals." (PMID 27578213, 2016). "Tumor tissues from HFD-IF mice diminished C5, IL-1β, CCL3, and CXCL2 protein levels compared to those from HFD mice, indicating that IF attenuates obesity-induced inflammatory conditions in the tumor microenvironment." (PMID 38999849, 2024). "Strikingly, ob-dT bASCs already displayed an enhanced gene expression of CXCL2, CXCL1, CXCL3, FGF2 and CCL2, compared to ln-dT bASCs, suggesting a crucial impact of obesity on bASCs." (PMID 36710348, 2023). "Mouse CXCL1 and CXCL2 (CXCL1/2) are well-established functional homologs of human CXCL8 (IL8), whose expression is also induced by NF-κB36–38 in obesity and insulin resistance." (PMID 34686752, 2021). "Examination of the fibroinflammatory effects of obesity in MMP14LKO mice revealed that both WD and HFFC feeding in mice increased hepatic inflammatory marker gene expression—TNFα, CXCL2, CXCL9, TGFβ, and IL-1β—in WT mice, and this was attenuated in WD-fed MMP14LKO mice." (PMID 39282008, 2024).